LOXL2 (lysyl oxidase like 2)
Diseases named in the same sentence as LOXL2 in open-access papers (continued):
Sharing a sentence is not in itself a finding about the gene and the disease.
esophageal cancer (5 papers, 2008 to 2025). A primary or metastatic malignant neoplasm involving the esophagus. "To study the contribution of either full-length LOXL2 or its spliced isoforms to tumor cell proliferation, we performed loss- and gain-of function assays in esophageal cancer cells." (PMID 36209516, 2022). "For instance, LOXL2 is remarkably up-modulated in colonic and esophageal cancers and its high expression is associated with unfavorable prognosis." (PMID 34308761, 2021). "Cell fractionation indicated that both LOXL2 and L2Δ13 cause a shift of aldolase A from the cytoskeletal to the cytosolic fraction, whereas silencing LOXL2 expression inhibited the mobilization of aldolase A of esophageal cancer cells." (PMID 36209516, 2022). "High level expression of full-length LOXL2, as well as its L2Δ13 isoform, promotes cell migration and invasion of esophageal cancer cells in vitro and in vivo, which is further linked to tumor metastasis and poor clinical outcome of esophageal cancer patients." (PMID 36209516, 2022). "LOXL2 depletion also greatly decreased the accumulation of neutral lipids in cell metabolism of these esophageal cancer cells." (PMID 36209516, 2022). "Mobilization of aldolase A was prevented following the silencing of LOXL2 expression in esophageal cancer cells, which were conversely restored by re-expression of LOXL2 or L2Δ13 in cells silenced for LOXL2 expression." (PMID 36209516, 2022). "High level expression of LOXL2/L2Δ13 combined with decreased acetylation of aldolase-K13 predicted poor clinical outcome in patients with esophageal cancer." (PMID 36209516, 2022). "Confocal immunofluorescence staining indicated that either LOXL2 or L2Δ13 colocalized with aldolase A in esophageal cancer cells which express all of these proteins endogenously." (PMID 36209516, 2022). "Loss- and gain-of-function assays showed that, in addition to the effects of LOXL2 on tumor cell invasion and tumor metastasis [16,], both L2Δ13 and LOXL2 promote esophageal cancer cell proliferation and tumor growth in xenograft experiments." (PMID 36209516, 2022). "LOXL2 and its catalytically inactive isoform L2Δ13 function as new deacetylases to promote metabolic reprogramming and tumor progression in esophageal cancer by directly activating glycolytic enzymes such as aldolase A." (PMID 36209516, 2022). "We previously found that LOXL2 predominantly regulated genes involved in several metabolic pathways in esophageal cancer, such as carbohydrate metabolism and lipid metabolism." (PMID 36209516, 2022). "More importantly, we extended these results to identify a subgroup of esophageal cancer that exhibit LOXL2 or L2Δ13 combined with decreased acetylation of aldolase-K13." (PMID 36209516, 2022). "Intriguingly, only one of the LOXL2/L2Δ13-interacting proteins, aldolase A, was hyperacetylated in LOXL2-silenced esophageal cancer cells, while re-expression of LOXL2 or L2Δ13 reduced the elevated acetylation level of aldolase A." (PMID 36209516, 2022). "We subsequently combined the states of either LOXL2 or L2Δ13 and K13-acetylated aldolase A to develop molecular models for predicting the clinical prognosis of patients with esophageal cancer." (PMID 36209516, 2022). "In contrast, depletion of LOXL2 in esophageal cancer cells inhibits glycolysis, suggesting that glycolysis induced by L2Δ13/LOXL2 contributes to the Warburg effect and tumor progression." (PMID 36209516, 2022). "Considering the serendipity of LOXL2 associated with other genes, this study used the GEPIA database to screen out genes similar to LOXL2 in esophageal cancer and applied the STRING database to construct a co-expression network for GO and KEGG enrichment analysis of similar genes." (PMID 36995521, 2023). "Importantly, in situ proximity ligation assay (PLA) detected LOXL2/L2Δ13-aldolase A complexes in esophageal cancer cells, confirming that this interaction also exists in vivo." (PMID 36209516, 2022).
esophageal cancer (continued). "We have previously identified a novel LOXL2 splice variant L2Δ13 (mRNA, GenBank accession number KF928961; protein, GenBank accession number AHJ59530) in human esophageal squamous cell carcinoma (hereinafter referred to esophageal cancer) cells." (PMID 36209516, 2022). "Furthermore, microarray data of patients with esophageal cancer also indicated that LOXL2 expression positively correlated with enhanced glycolysis and gluconeogenesis pathways in clinical settings." (PMID 36209516, 2022). "Consistently, depletion of LOXL2 greatly decreased ATP formation, glucose uptake and lactate buildup in TE1 and KYSE510 esophageal cancer cells." (PMID 36209516, 2022). "To characterize the molecular mechanisms by which LOXL2/L2Δ13 regulates metabolism, we analyzed the metabolic status of esophageal nonmalignant cells and esophageal cancer cells in the presence and absence of LOXL2." (PMID 36209516, 2022).
lung adenocarcinoma (5 papers, 2021 to 2025). A carcinoma that arises from the lung and is characterized by the presence of malignant glandular epithelial cells. "LOXL2 is associated with the progression of lung adenocarcinoma and poor prognosis of NSCLC." (PMID 35634481, 2022). "The clinical relevance of VM is underscored by the development of “VM-scores” based on EPHA2, LAMC2, and LOXL2 genes, which serve as independent prognostic markers in lung adenocarcinoma." (PMID 40786517, 2025). "It was recently documented that knockdown of LOXL2 expression in specific lung adenocarcinoma cell lines decreased collagen fibrillar alignment." (PMID 34011405, 2021). "The expression of the 6 key genes (FKBP3, GPI, LOXL2, IL22RA1, GPR37, has-miR-148a-3p) in lung adenocarcinoma patients with different tumor stages, T stages, N stages and M stages." (PMID 34040139, 2021).
metastatic disease (5 papers, 2016 to 2021). "Baseline serum levels of LOXL2, a marker of collagen cross-linking, were higher in those patients with metastatic disease (p < 0.0001) or who were NED and being treated in the adjuvant setting (p = 0.04) compared with healthy controls." (PMID 34426581, 2021). "Additionally, tumor-associated CD8 cell numbers were comparable between the peripheral and inner regions of primary tumors, but were further increased in primary and metastatic tumors relative to total tumor cells when LOXL2 inhibition or knockdown was combined with anti-PD-L1." (PMID 32908154, 2020). "Histological analyses verified that LOXL2 suppression decreased lung metastatic burden and increased CD8 cell infiltration into both the primary and metastatic tumors." (PMID 32908154, 2020). "We found epithelial marker genes, Krt18, Epcam, Dsp, were downregulated in the metastatic tumors, while genes that promote EMT, Zeb2, Loxl2, and Plau were upregulated." (PMID 31881983, 2019).
Obesity (5 papers, 2017 to 2024). Accumulation of substantial excess body fat. "In addition, since L2Δ13 leads to adipose loss, enhancing LOXL2 gene splicing to form L2Δ13 may represent a potential strategy for treating obesity." (PMID 36060061, 2022). "LOXL2 can promote tumor development and influence obesity by regulating glycometabolism and lipid metabolism." (PMID 38810697, 2024). "Additionally, circulating LOXL2 levels have not been measured in many clinical cohorts, so the effect of factors such as age, sex, obesity, cardiovascular disease, and liver disease on LOXL2 levels are unknown." (PMID 28782046, 2017).
bladder cancer (4 papers, 2018 to 2025). "Integration analysis of two bladder cancer scRNA-seq datasets suggested a positive correlation between lysyl oxidase like 2 (LOXL2) expression in CAFs and expression of CD206, a marker of M2-type macrophage polarization." (PMID 40453088, 2025). "Furthermore, LOXL2 was identified as a potential prognostic biomarker and predictor of response to immunotherapy in bladder cancer." (PMID 40453088, 2025). "Similarly, it was shown that LOXL2+ iCAFs as greatly correlated with poor prognosis in bladder cancer through integrated analysis, further supporting our findings." (PMID 41395115, 2025). "LOX and LOXL2 reportedly promote kidney carcinoma tumorigenesis, while LOX, LOXL1 and LOXL4 suppress bladder cancer growth." (PMID 29732010, 2018).
chronic kidney disease (4 papers, 2018 to 2026). Impairment of the renal function secondary to chronic kidney damage persisting for three or more months. "In a previously published single-cell sequencing dataset of human kidneys with and without chronic kidney disease (CKD), we observed that the LOXL2 gene was predominantly enriched in myofibroblast populations." (PMID 41607781, 2026).
glioblastoma (4 papers, 2016 to 2025). The most malignant astrocytic tumor (WHO grade IV). "O-GlcNAcylation of WTAP promotes glioblastoma malignant progression by stabilizing LOXL2 mRNA via an m6A-IGF2BP2-dependent manner." (PMID 40651967, 2025). "To investigate the impact of the LOX family on glioblastoma, we analyzed the expression of LOX family members (LOX, LOXL1, LOXL2, LOXL3, and LOXL4) in normal human astrocytes (Heb) and glioblastoma cell lines (T98G and LN-229)." (PMID 40270974, 2025).
head and neck cancer (4 papers, 2021 to 2025). A primary or metastatic malignant neoplasm affecting the head and neck. "For example, LOXL2-enriched EVs mediate hypoxia-induced premetastatic niche formation in the lungs and are associated with poor outcome in head and neck cancer." (PMID 40662366, 2025). "Also, LOXL2 secreted by hypoxic head and neck cancer stimulates pre-metastatic niche formation and drives local invasion of non-hypoxic head and neck cancer cells." (PMID 39917412, 2025).
Insulin resistance (4 papers, 2018 to 2024). Increased resistance towards insulin, that is, diminished effectiveness of insulin in reducing blood glucose levels. "As previously suggested, there is a certain relationship between insulin resistance and LOXL2." (PMID 31426495, 2019).
lymph node metastasis (4 papers, 2017 to 2021). "LOXL2 expression in stromal cells was significantly associated with tumor invasion depth, lymph node metastasis, lymphatic invasion, venous invasion, peritoneal dissemination, and survival in GC patients." (PMID 35126449, 2021). "However, the overexpression of either SP1 or LOXL2 did not significantly correlate with poor clinical outcomes including lymph node metastasis, depth of invasion, or lymphovascular invasion." (PMID 30976063, 2019).
myelofibrosis (4 papers, 2014 to 2026). A partial or complete replacement of the bone marrow stroma by fibrous tissue. "One such inhibitor is PXS-5055, which reduced LOX and LOXL-2 activity when administered to myelofibrosis patients that had developed a resistance to ruxolitinib in a phase 1 trial." (PMID 33738462, 2020). "Our proposed designs are motivated by a phase II trial of a lysyl oxidase homolog 2 (LOXL2) inhibitor, an MTA, in adult patients with primary, post polycythemia vera, or post essential thrombocythemia myelofibrosis." (PMID 25074481, 2014).
osteoarthritis (4 papers, 2017 to 2021). A noninflammatory degenerative joint disease occurring chiefly in older persons, characterized by degeneration of the articular cartilage, hypertrophy of bone at the margins and changes in the synovial membrane. "To dissect the underlying function of LOXL2 proteins in the osteoarthritis chondrocytes induced by mechanical stress, we first manipulated a study to assess if LOXL2 expression correlate with the severity of osteoarthritis." (PMID 34426599, 2021). "LOXL2 relieves osteoarthritis by promoting a chondroprotective response that includes, induction of anabolic gene expression, remodeling of the extracellular matrix and attenuation of the expression of catabolic genes." (PMID 32621591, 2020). "The goal of this study was to evaluate the potential of LOXL2 to act as an anabolic agent in cartilage affected by osteoarthritis (OA)." (PMID 28764769, 2017).
cardiomyopathy (3 papers, 2016 to 2026). A disease of the heart muscle or myocardium proper. "The clear separation of control and cardiomyopathy samples in the LOXL2–COLLAGEN correlation graphs indicates a functional role of LOXL2 elevation in the pathogenesis of human fibrotic hearts." (PMID 27966531, 2016). "Furthermore, the consistent findings of mouse and human heart tissue studies suggest an evolutionary conservation of LOXL2-based interstitial mechanism of cardiomyopathy." (PMID 27966531, 2016).
cholangiocarcinoma (3 papers, 2021 to 2023). A carcinoma that arises from the intrahepatic biliary tree (intrahepatic cholangiocarcinoma) or from the junction, or adjacent to the junction, of the right and left hepatic ducts (hilar cholangiocarcinoma). "An experimental research has verified that interactions of LOXL2 with GATA6 can induce the expression of VEGFA, which may promote angiogenesis in cholangiocarcinoma subcutaneous tumorsand tumor growth." (PMID 33478536, 2021).
glaucoma (3 papers, 2008 to 2019). Increased pressure in the eyeball due to obstruction of the outflow of aqueous humor. "LOXL2 could be a promising therapeutic target for reducing scar formation after glaucoma surgery." (PMID 26818010, 2015).
Hyperglycemia (3 papers, 2016 to 2025). An increased concentration of glucose in the blood. "Furthermore, LOXL2 (cg04028450) is associated with hyperglycemia, giving weight to the present study’s observed significant association with blood glucose levels and HbA1c." (PMID 39415250, 2024). "Building on evidence of hyperglycemia-triggered endothelial LOX/LOXL2 overexpression, we provide causal evidence that GEnC-secreted LOX/LOXL2 enzymes directly induce mesangial cell dysregulation, driving oxidative stress, fibrosis, and collagen synthesis." (PMID 41355449, 2025).
kidney cancer (3 papers, 2010 to 2024). Primary or metastatic malignant neoplasm involving the kidney. "The 26 down-regulated microRNA had 170 direct up-regulated mRNA targets, including oncogenes VEGFA, LOX, LOXL2 and FAS, well known to be involved in kidney cancer." (PMID 20420713, 2010).
liver disease (3 papers, 2017 to 2018). "As myofibroblasts regulate portal resistance, LOXL2 may also contribute to development of portal hypertension." (PMID 28480218, 2017). "In addition, our study demonstrated the novel correlation of soluble LOXL2 and hepatic LOXL2 expression with portal hypertension." (PMID 28480218, 2017).
lung disease (3 papers, 2017 to 2024). "LOXL2 has been associated with replicative and stress-induced senescence in previous studies of skeletal muscle and lung diseases, whereas it is rarely reported in oncogene induced cellular senescence." (PMID 38922489, 2024). "LOXL2 has been reported in the process of senescent morphogenesis in fibroblast and epithelial cells, leading to skeletal muscle fibrosis and lung diseases, but is rarely analyzed in tumor research." (PMID 38922489, 2024). "In summary, our study provides a comprehensive analysis of the LOX/L family in fibrotic lung disease and indicates prominent roles for LOXL2/3 in fibroblast activation and LOX/LOXL2 in IPF." (PMID 28273952, 2017). "Additionally, PAT-1251 (newly designated GB2064), which targets LOXL2, has been used in phase 1 clinical trials for the treatment of lung disease as well as metastatic breast cancer." (PMID 34771678, 2021).
Nephropathy (3 papers, 2018 to 2021). A nonspecific term referring to disease or damage of the kidneys. "Across chrB1:34,395,302–38,202,712, variants segregated in cases in LOXL2, previously implicated in nephropathy and retinopathy in T2D patients, indicating these may play a critical role in the progression to FDM." (PMID 33154479, 2020). "In the present study, we demonstrated that CsA- induced nephropathy is associated with LOX and LOXL2 overexpression in the kidney." (PMID 34127702, 2021). "Collectively, our study suggests that Pan-LOX and LOXL2 inhibition can attenuate progressive nephropathy due to CsA administration." (PMID 34127702, 2021). "The induction of renal lysyl oxidases, in particular LOX and LOXL2 has been shown in several kidney disease models." (PMID 29930330, 2018). "Compared to animals with CsA nephropathy that were treated with the vehicle control, those treated with pan-LOX and LOXL2 inhibitors showed significant reductions in the protein expression of α-SMA (P < 0.05), suggesting reduced myofibroblast activation." (PMID 34127702, 2021).
oral cancer (3 papers, 2019 to 2021). "There is now a considerable body of literature indicating that elevated LOXL2 in particular is associated with a variety of cancers, including oral cancer." (PMID 31086173, 2019). "The role and mechanism of active LOXL2 in promoting oral cancer was evaluated and employed a novel LOXL2 small molecule inhibitor, PSX-S1C, administered to immunodeficient, and syngeneic immunocompetent orthotopic oral cancer mouse models." (PMID 31086173, 2019). "The data suggest that LOXL2 enzyme activity significantly promotes oral cancer to cervical lymph node metastasis." (PMID 31086173, 2019). "In differentiated oral cancer, LOX and LOXL2 were clearly expressed in tumor nests, and in associated elongated cells with a mesenchymal morphology." (PMID 31086173, 2019). "In summary, we show that tumor cell LOXL2 targets proximal mesenchymal fibrogenic cells by a novel microenvironment tumor-promoting mechanism, while small molecule LOXL2 inhibition can improve oral cancer outcomes." (PMID 31086173, 2019). "The successful use of a selective LOXL2 pharmacologic inhibitor to address oral cancer in two in vivo mouse models provides pre-clinical evidence that supports the notion that similar inhibitors may have therapeutic potential against oral cancer." (PMID 31086173, 2019). "XS-5382A, an oral LOXL2 inhibitor, has been shown to slow tumor growth and reduce collagen accumulation in LY2 oral cancer models and is currently being investigated in Phase 1 clinical trials in healthy adults (Clinical trial identifier: NCT04183517)." (PMID 35126449, 2021). "Although complete inhibition of cancer growth was not accomplished, the possibility is raised that LOXL2 inhibitors in combination with other therapeutic approaches including immunotherapy could result in potentially effective strategies to address oral cancer." (PMID 31086173, 2019).
skin cancer (3 papers, 2017 to 2022). "It has been shown previously that Loxl2 overexpression increases and Loxl2 loss-of-function decreases skin tumour burden and malignant progression by affecting epidermal differentiation." (PMID 29953488, 2018). "Also, LOXL2 and LOXL4 mRNA levels were markedly upregulated in α11-deficient skin tumors, on average by 300-fold and 50-fold relative to the controls, respectively." (PMID 36003785, 2022). "The high levels of LOX, LOXL2, and LOXL4 transcripts in α11-deficient CAFs are congruent with the observed formation of extensive, linear collagen bundles and a shift toward stiffer skin tumor tissue in this mouse strain." (PMID 36003785, 2022). "We speculate that the increased skin tumour burden in Loxl2 gain-of-function mice is induced by LOXL2’s intracellular epidermal functions, such as inhibition of terminal differentiation, promoting epithelial-mesenchymal transition or altering epithelial cell polarity." (PMID 29953488, 2018).